CD4 (CD4 molecule)
Diseases named in the same sentence as CD4 in open-access papers (continued):
Sharing a sentence is not in itself a finding about the gene and the disease.
tumor (continued). "Similarly, in tumor subgroups with decreased CD8+ T cells (HR=1.55, p=0.0045) and decreased CD4+ T cells (HR=1.47, p=0.018), high COL1A1 expression was significantly associated with poor prognosis in OC." (PMID 39845977, 2024). "Our results indicated that the removal of CD8+ T cells or both CD4+ and CD8+ T cells entirely negated the tumour regression triggered by the combination therapy, while the elimination of only CD4+ T cells did not have a notable effect." (PMID 39095323, 2024). "Tumor cells expressing MHC-II potentially secrete immunostimulatory exosomes, engage in direct interactions with CD4+ T cells to influence their polarization and activation, or secrete antigens that are endocytosed and presented by professional antigen-presenting cells (pAPCs)." (PMID 38596689, 2024). "In tumor immunity, type one conventional DCs (cDC1s) process and cross-present antigens to activate CD8+ T cells, while cDC2s are essential for priming antitumor CD4+ T cell responses." (PMID 38538718, 2024). "Human CD4+ CAR-T cells demonstrated similar findings: an increase in central memory T cells, sustained antitumor efficacy under hypoxia, and prolonged cytokine secretion when cocultured with EGFRvIII-positive tumor cells under hypoxic conditions." (PMID 38386420, 2024). "Tumour tissue from one patient demonstrated increased numbers of CD4+ and CD8+ T cells along with an absence of Treg cells and a reduced number of CD11b+ cells after administration of DNX-2401." (PMID 38732225, 2024). "Likewise, absolute numbers of peripheral blood CD4+ Treg cells were decreased in HCC and CCA patients before surgery, and significantly increased after tumor resection." (PMID 39408071, 2024). "TIL markers such as CD3, CD4, CD8, and FOXP3 can predict the survival outcomes of OSCC patients, but do not serve as independent prognostic markers as found with conventional factors (i.e. nodal status, tumor differentiation and PNI)." (PMID 38926643, 2024). "We further stained CD4+ and CD8+ T cells in the tumor microenvironment of different groups of mice." (PMID 39205202, 2024). "Moreover, through tumor-infiltrating lymphocyte analysis, they enhanced the levels of granzyme B+, CD3+, CD4+, and CD8+ T-cells post treatment with the glycosidic compounds." (PMID 38660299, 2024). "Compared to controls, the CD8+/CD4+ T cell ratio in TME was significantly increased by CpG/R848/Adpgk-codeliverying NPs (CRA-NPs) + an anti-programmed death-1 antibody (αPD-1), indicating a positive response to tumor therapy." (PMID 38355548, 2024). "CD4 + T cells can directly secrete cytokines such as IFN-α, TNF-γ, IL-2, which have anti-tumor effects, and also activate immune effector cells such as CD8 + T cells and NK cells to indirectly exert anti-tumor effects." (PMID 38834662, 2024). "The findings described in this study highlighted that the depletion of CD4+ or CD8+ T cells in MOC2-CIITA vaccinated mice resulted in the nullification of the immune response against tumors, as MOC2-CIITA tumor cells were growing with a similar kinetics as the MOC2 parental cells." (PMID 39035008, 2024). "Induce the activation of both tumor specific CD8+ and CD4+ T lymphocytes." (PMID 39334825, 2024). "Remarkably, outgoing signals from CXCL10+ M1 Macrophages to B cells, CD4+T cell, CD8+T cells and Endothelial cell were more abundant and stronger in tumor group compared with normal group, while the output signal of SPP1+ macrophages cell was reduced in the tumor group." (PMID 39170612, 2024). "The tSNE plot shows an increase in the frequency of CD3+, CD4+ and CD8+T cells, CD69, PD1 and PD-L1 expression on T cells, and a decrease in the frequency of epithelial cells after treatment, indicating enhanced anti-tumor immune responses." (PMID 38516270, 2024).
tumor (continued). "Most importantly, MMP11 was positively associated with M0-macrophages and negatively associated with M1-macrophages, NK cells activated, NK cells resting, T cells CD4 memory activated, and T cells follicular helper, indicating the remarkable interactions of MMP11 with tumor immunology." (PMID 39239548, 2024). "In the tumor group, a significant variation between 5mM SB and no SB was only seen without glucose, but the CD4+ T cells tended to increase also in the presence of glucose, whereas in the smoker group no statistically important changes where seen." (PMID 38650948, 2024). "While the importance of CD4+ T cells in YUMM1.7 tumors was clear, the magnitude may depend on the tumor model, as regressing B16 tumors showed higher CD8+ T cell infiltration." (PMID 39236156, 2024). "We obtained scRNA-seq data of the tumor microenvironment in LIHC from the GSE149614 dataset and performed clustering analysis on ten distinct cell types, including epithelial cells, CD4+ T cells, CD8+ T cells, B cells, TAMs, Kupffer cells, DCs, LVECs, LSECs, and pericytes." (PMID 39132167, 2024). "Specifically, this was driven by a significant increase in CD4 + T cells (padj=1.97E-04), which play critical roles in effective anti-tumor immunity, and not CD8 + T cells (padj=0.44)." (PMID 39614348, 2024). "Patients with B7-H2high tumor cells showed advanced TNM stage and N+ stage with decreased OS, MFS, or DFS, and this sub-cohort was featured with a trend of diminished CD4+ T cells and CD8+ cells in tumor center in situ, which positively correlated with PD-L1 and IL10." (PMID 38554152, 2024). "Importantly, immune CD4+ T cells were able to strongly reduce MOC2-pc tumor growth in 89% of the animals and confer tumor protection in the remaining 11% of mice." (PMID 39035008, 2024). "Functionally, USP7 inhibition in the CT‐26 syngeneic mouse model led to increased recruitment of CD8+ lymphocytes to the tumour but did not affect CD4+ or regulatory T‐cells." (PMID 38602256, 2024). "Tumours with positive PD-L1 IC expression were more likely to have high Foxp3+CD4+ T cell infiltration in tumour islets, as well as tumours with positive PD-L1 TPS, IC, or CPS were more likely to have low IL-17A+CD4+ T cell infiltration in the tumour stroma." (PMID 39409156, 2024). "This underlying mechanism may explain our observed strong associations between NLRC4 tumor expression with DC2/DC3 and CD4+/CD8+ T cell infiltration into patient tumors for antigen presentation and tumor killing, respectively." (PMID 38652550, 2024). "PD-1 expression, but not CD69 expression, was significantly enhanced on CD4+ T cells in the treated tumor." (PMID 39410025, 2024). "In addition, the results of FCM showed highly significant infiltration of CD4+ and CD8+ T cells in the primary tumor tissue of the PSB@Nb1.33C/mRNA nanosystem after NIR laser irradiation, which was 2.56‐fold more than that of the control group." (PMID 38742454, 2024). "Denoted on the table (*), patient 10 had a lower percentage of CD4 and CD8 positive cells from baseline tumour samples compared to the selected responding patients (Pt 2, 11, 13, 15), potentially indicating a difference in the immune profile or immune activity in that case." (PMID 38804839, 2024). "Since CCL4 mainly recruits CD4+ T cells, CCL4 upregulation may lead to a greater proportion of infiltrating regulatory T (Treg) cells in the tumor and enhance local immunosuppression." (PMID 39483474, 2024). "Furthermore, MDSCs can suppress CD4+ and CD8+ T cell responses via several mechanisms, first by upregulating PD-L1 and inhibiting T cell activation and tumor tolerance." (PMID 39273502, 2024). "Further in vivo and in vitro analyses reveal that zebularine stimulates cGAS-STING-NF-κB/IFNβ signaling to enhance tumor cell immunogenicity and upregulate antigen processing and presentation machinery (AgPPM), which promotes effective CD4+ and CD8+ T cell-mediated killing of tumor cells." (PMID 38755254, 2024).
tumor (continued). "Thus, anti-CTLA-4 and anti-PD-1 mAbs restore anti-tumor activity by facilitating the differentiation or the reactivation of tumor-reactive cytotoxic CD8+ T cells and of helper CD4+ T cells." (PMID 38318190, 2024). "In CTCL, malignant CD4 (+) T cells interact with various components such as CD8 (+) T cells, dendritic cells, macrophages, as well as ncRNAs, and other critical actors, to form the tumor microenvironment (TME)." (PMID 39256366, 2024). "We performed non-negative matrix factorization based on the proportions of these cell types within the tumor microenvironment (TME) for each sample, categorizing them into six groups: Epithelialhi TME, Myeloidhi TME, B cellhi TME, CD8+ T cellhi TME, CD4+ T cellhi TME, and Stromalhi TME)." (PMID 38414015, 2024). "Naïve CD4 + T cells were not present in the tumor microenvironment of RCC, hence no color was observed." (PMID 39465721, 2024). "CD154 staining showed that TCR135-CD4 but not TCRneg-CD4 cells were activated by C666-1-EBNA1 tumor cells." (PMID 38412034, 2024). "In a word, rAd.mDCN.mCD40L might induce anti-tumor immune responses via activating CD8+ T effector cells and CD4+ T memory cells, while downregulating MDSCs and Tregs." (PMID 39306655, 2024). "E2 can cause immunosuppression through inhibition of cytotoxic T-cells- and NK cell-mediated tumor cell elimination, while E2-treated ERα-expressing CD4+CD25- T-cells regain CD25 expression, so such transformed CD4+CD25+ T-cells then manifest an immunosuppressive Treg phenotype." (PMID 38672656, 2024). "Conversely, the administration of anti‐CD4 antibody did not affect the PS‐mediated anti‐tumor response." (PMID 38900071, 2024). "Research has indicated that CD4 T cell assistance is instrumental in sustaining and enhancing the functionality of effector CD8 T cells within tumor microenvironments, and recent studies have highlighted the pivotal role of CD4 T cell epitopes in augmenting CD8 T cell response in human cancers." (PMID 39336774, 2024). "In tumour microenvironment, CD11b+ dendritic cells with high expression levels of IL23 and TGF‐β could induce IL10+CD4 Tregs and promote tumour progression." (PMID 37748771, 2024). "Tregs, characterized by CD4+/CD25+/FoxP3+ expression, can inhibit CD8+ T cell cytotoxicity by secreting immunosuppressive cytokines such as interleukin-10 (IL-10) and transforming growth factor-beta (TGF-β), thereby facilitating tumor immune evasion." (PMID 39769460, 2024). "Tumor-specific T cells refer to T cells capable of recognizing tumor antigens and initiating an immune response against them, including CD8+ cytotoxic T cells and CD4+ helper T cells." (PMID 38370407, 2024). "Although OX40 antibody alone tended to attenuate CT26 tumor growth at the target and non-target lesions, neither CD4 nor CD8 T cell number increased." (PMID 39534532, 2024). "Furthermore, Res-pretreated NK cells exhibited a significantly enhanced recruitment of macrophages, CD4+ T cells, and CD8+ T cells in both tumor tissues and spleen compared to the NK cell group." (PMID 38891683, 2024). "CD4+ T cells, known for their helper function, play a pivotal role in regulating immune responses, whereas CD8+ T cells are recognized for their cytotoxic activity against tumor cells." (PMID 39459546, 2024). "The γ/δ+ lymphocytic tumor cells displayed a complete loss of CD2, partial downregulation of CD5, and showed no expression of CD4, CD30, CD56, TdT, or TCRαβ (clone 8A3/BetaF1)." (PMID 39091627, 2024). "We report that in addition to attracting CXCR3+ T cells to tumor sites a key role of CXCL9 and CXCL10 is in inducing a self-feeding feedback loop that accelerates effector/cytotoxic activities of both CD4+ and CD8+ T cells while downregulating immunoregulatory protein TIM3." (PMID 39474427, 2024).
tumor (continued). "The transcriptional differences corresponded to a modified tumor microenvironment as assessed by multiplex immunofluorescence on FFPE slides, as immune cells, particularly CD8+ and CD4+ T cells, infiltrated PCK+ tumor tissue considerably in M_CL1, while very few were present in M_CL2 samples." (PMID 38988711, 2024). "CHD4 insufficiency reduced immune suppression, as could be observed by elevated CD4+ and CD8+ T cell populations within the tumor, and enhanced the effectiveness of antitumor T-cell responses in melanoma-bearing mice treated with an anti-PD-1 antibody." (PMID 39519018, 2024). "This treatment was safe, inducing a strong CD4+ T cell-mediated immune response, independent of anti-PD-1 immunotherapy, both in peripheral blood and at the tumor site." (PMID 39202398, 2024). "T cells represent the 34.8% of the tumor infiltrating cells (range 19.7-51.3%; n=8 PDAC), with CD8+ and CD4+ T cells counting for the 19.6% (range 8.4-32.2%; n=8) and 15.19% (range 5.1-26.2%; n=8) of T lymphocytes, respectively (C: CD3+, CD8-, white arrowheads, CD3+, CD8+, white arrows)." (PMID 39575252, 2024). "Together, our study underscores a synergistic inflammatory immune response orchestrated by highly immunogenic tumor cells and CXCL13+CD4+ T cells in HPV+ OPSCC, offering useful insights into strategy development for patient stratification and effective immunotherapy in OPSCC." (PMID 39105803, 2024). "However, in gliomas, TREM2 inhibits tumor progression by enhancing the phagocytosis of tumor cells and promoting MHC-II-related CD4+ T cell responses." (PMID 39135069, 2024). "We also identified that the CD8+ and CD4+ T cell counts and Treg cell densities in tumours were significantly higher in responders than in non-responders, which is consistent with the findings of previous studies on NSCLC." (PMID 38399453, 2024). "Chemokines can serve pro- or anti-tumor functions, with the chemokines CXCL9 and CXCL10, ligands for CXCR3, being of the most interest in the anti-tumor category due to their ability to attract effector CD8+ and CD4+ T cells." (PMID 38803496, 2024). "Other studies have reported models focusing on one or on parallel pathways of inhibitory factors induced by Treg, TGF-β and/or IL-10 that promote tumor growth and reduce the cytotoxicity of effector cells (i.e., CD8+ cells and others such as DC, CD4+ helper T cells, and IL-2)." (PMID 39598584, 2024). "Finally, the combination therapy further and markedly increased tumor‐infiltrating CD8 and CD4 cells, indicating a strong translational potential for this new treatment strategy in PDAC." (PMID 39297408, 2024). "Similarly, the blockade of both CXCR4 and PD-1 in a murine model of ovarian cancer revealed increased CD4+ and CD8+ T cell tumor infiltration." (PMID 38786066, 2024). "In the B16F10 tumor-bearing mouse model, MSNM@CY1-4 can significantly inhibit the activity of IDO in blood and tumor tissues, ameliorate the immunosuppressive TME and TDLN, significantly reduce Tregs infiltration, increase CD4+ T cells and CD8+ T cells infiltration, and improve anti-tumor effects." (PMID 39728172, 2024). "Additionally, the percentage of CD3+CD8+ was higher than that of CD3+CD4+ cells, indicating that a large number of cytotoxic T-cells (CD8+) induced a strong anti-tumor response." (PMID 38173045, 2024). "Importantly, even though the mission of killing a tumor is assigned to CD8+ T cells, in recent studies CD4+ T cells were proven to exhibit cytotoxic activity towards a tumor as well." (PMID 38892394, 2024). "Within the tumor center, CD68 counts were correlated with CD4, CD8, and CD163 of the same region." (PMID 39338178, 2024). "The reduction in CD4+ T cells may reflect an impact on immune regulation, while the increase in CD8+ T cells suggest cytotoxic activation against tumor cells." (PMID 39339213, 2024).
tumor (continued). "This selective recruitment of CD8+ T cells over CD4+ T cells may be an advantageous mechanism in CRC, where increased cytotoxic activity can directly limit tumor progression." (PMID 39791120, 2024). "Importantly, the expression level of tumor exosomal ENPP1 shown an inverse correlation with CD8+ T cells and CD4+ T cells infiltration, respectively." (PMID 38498770, 2024). "In addition, the Chinese herbal compound SanHuang decoction and ADAMTS18 have a synergistic effect by increasing the proportion of CD8+ and CD4+T cells and reducing the ratio of CD45+/PD-L1 to increase tumor immune infiltration and inhibiting immune escape." (PMID 38482210, 2024). "As the flow cytometry result of 1G11 increases CD3+, CD4+ and CD8+ T cell infiltration in tumor tissue, it may be able to act synergistically with anti-PD1 antibodies or other immune checkpoint inhibitors." (PMID 39169307, 2024). "Additionally, there is a significant elevation in the levels of central memory CD4+ T and CD8+ T cells, which have the potential to differentiate into effector CD4+ T and CD8+ T cells and exert anti-tumor effects." (PMID 38961429, 2024). "Next, knowledge of CCR7+ DC ontogeny remains incomplete, particularly the relative contribution of cDC subsets or monocytes to heterogeneous tumour-residing CCR7+ DC states, which may influence their ability to support CD8+ versus CD4+ T cell responses." (PMID 38267413, 2024). "Furthermore, tumor-bearing CD11c:DTA mice showed an enhanced expression of TIM-3 on CD4+ T cells and PD-1 and TIM-3 on CD8+ T cells in Spl as compared with those obtained from tumor-bearing WT mice." (PMID 39206204, 2024). "NK cells activated, monocytes, Tregs, B cells naive, T cells CD8, T cells CD4 memory resting, and macrophages M2 were lower in CDKN2A-MUT or DEL patients’ tumor tissue than in CDKN2A-WT patients, implying an immune cold tumor immune microenvironment in TCGA pan-cancer with CDKN2A VAR." (PMID 38822443, 2024). "Although CD8+ CAR-T cells are considered the leading player of tumor killing, several studies have shown that the presence of both CD4+ and CD8+ CAR-T cells with a defined ratio within the final product can result in a better and more durable anti-tumor function." (PMID 39624236, 2024). "In patients with triple‐negative breast cancer, higher frequencies of tumour‐infiltrating CD4+ T cells expressing PD‐1 and CD39 and CD8+ T cells expressing CD39 corresponded to higher frequencies of these phenotypes in the periphery." (PMID 39162097, 2024). "We then compared the expression profiles of tumor-specific CD4 + T cells and non-tumor-specific CD4 + T cells, as well as tumor-specific CD8 + T cells and non-tumor-specific CD8 + T cells." (PMID 39033098, 2024). "Additionally, in the tumor tissues of mice implanted with LLC‐PRPS2‐shCCL2 cells, we observed a significant increase in the percentage of CD4+ T cells and CD8+ T cells, accompanied by a significant decrease in the percentage of TAMs, M‐MDSC, and PMN‐MDSC." (PMID 38952044, 2024). "Our findings demonstrated that diverse immune cell subsets (MDSCs, Tregs, CD4+ or CD8+ T cells, and DCs) across tumor tissues and lymphoid organs were differentially regulated by oAd/APP+DC combination therapy that were suggestive of systemic antitumor immune response." (PMID 38835775, 2024). "Moreover, Cluster1 showed a higher abundance of immunosuppressive cells such as regulatory T cells and CD4 T cells, while Cluster2 exhibited higher expression of CD8 T cells, suggesting an active and potentially effective anti-tumor immune response." (PMID 38341586, 2024). "In cGAS- and STING-deficient mice, Mn treatment did not lead to an increase in CD8+ or CD4+ T cells, thus demonstrating Mn’s reliance on the cGAS pathway to alter the tumor microenvironment." (PMID 39050748, 2024). "Furthermore, our study establishes that both CD8+ and CD4+ TCR-T cells are able to infiltrate the tumor and persist for part of them, even after tumor escape." (PMID 38545119, 2024).